NF1 (neurofibromin 1)
Diseases named in the same sentence as NF1 in open-access papers (continued):
Sharing a sentence is not in itself a finding about the gene and the disease.
melanoma (continued). "Neurofibromin 1 (NF-1) mutation is associated with an increased risk of various tumors, including melanoma and breast cancer." (PMID 38254939, 2023). "NF1 mutations are prevalent in melanomas that are wild-type for BRAF and NRAS, NF1 are considered driver mutations in these patients." (PMID 37762707, 2023). "For instance, NF1 mutations are common in dedifferentiated melanomas as they are most often associated with melanomas arising on the highly sun-damaged skin of elderly individuals such as desmoplastic melanomas." (PMID 37373134, 2023). "Somatic NF1 mutations also occur in sporadic cancers including brain, lung, breast, ovarian, and melanoma." (PMID 37345107, 2023). "The prevalence of NF1 mutations in melanoma ranges from approximately 10% to 25%, depending on the specific cohort and the detection methods used." (PMID 37504268, 2023). "Amongst HRAS-mutant melanomas, 42% carried a co-altered NF1 mutation, significantly greater than in KRAS-/NRAS-mutant melanoma and other HRAS-mutant cancers (p<0.05)." (PMID 37503077, 2023). "NF1 mutations were also the most frequent in the cases we analyzed, consistent with the observation that dedifferentiated melanomas tend to occur on highly sun-damaged skin." (PMID 37373134, 2023). "Various mechanisms of acquired BRAFi resistance have been described in other tumors, mainly in melanoma, such as the loss of neurofibromin 1 (NF1)." (PMID 37958416, 2023). "Many somatic mutations, like nonsense mutations, frameshift mutations, splice site mutations or large deletions in the gene were identified in melanoma, resulting in loss-of-function of the NF1 protein." (PMID 37504268, 2023). "Mutations in the NRAS gene are found in 15–20% of melanomas, while mutations in the NF1 gene (neurofibromin-1) are found in 15% of melanomas." (PMID 37504268, 2023). "Somatic NF1 (neurofibromin 1) mutations are observed in a subset of melanoma cases, with varying frequencies reported across studies." (PMID 37504268, 2023). "Previous CRISPR screen of CREs on melanoma cells has been performed on several critical genes, including NF1, NF2, and CUL3, whose loss-of-function mutations resulted in vemurafenib resistance." (PMID 37904237, 2023). "As already demonstrated by numerous authors, when extensive molecular tests were available, most of the tumors discussed in this review carry mutations typical for melanomas, such as NF1, BRAF, and NRAS mutations." (PMID 37373134, 2023). "Somatic mutations in BRAF, NRAS, or neurofibromatosis 1 (NF1) are frequently observed in melanoma and their frequencies have been shown to depend on the cumulative amount of UV light and the anatomical site." (PMID 37658191, 2023). "NF1-mutated cutaneous melanoma comprises about 10–15% of all melanoma cases, while about 25% are Ras-mutated." (PMID 37345107, 2023). "Usually, melanomas occurring in heavily sun-damaged skin or desmoplastic melanomas show a significantly higher rate of NF1 mutations." (PMID 36614156, 2022). "Mutation in Neurofibromatosis Factor 1 gene (NF1) is the third most common mutation in melanoma and induces loss of the regulatory effect of NF1 on the RAS protein." (PMID 36686160, 2022). "Mutations in the NF1 gene leading to the inactivation of the encoded protein occur in melanoma with a frequency of 12–30% and are the third most frequent mutation in melanoma (after BRAF and NRAS)." (PMID 35565444, 2022). "Within the group of ARID1A mutated melanomas, the mutational pattern with NF1 mutated melanomas harboring the greatest mutational load." (PMID 35565222, 2022). "The prognosis of all patients with NF1-mutated melanoma has been reported to be significantly worse than patients with other mutation patterns." (PMID 36232957, 2022).
melanoma (continued). "Melanomas with NF1 mutation typically occur on chronically sun-exposed skin or in older individuals, show a high mutation burden, and do not express BRAF or NRAS mutations." (PMID 36232957, 2022). "Nevertheless, NF1-mutated melanomas have been associated with tumors with a high tumor mutation burden (TMB) that respond well to immunotherapy." (PMID 36614156, 2022). "Discovered in the early 1990s, the somatic NF1 gene mutations are mainly registered in older male patients and in the desmoplastic melanoma type, being frequently associated with other mutations of the RAS pathway." (PMID 35334544, 2022). "In melanoma and lung cancer, loss of NF1 conferred chemoresistance to cancer cells through inhibition of kinases and the RAS signaling pathways." (PMID 35130920, 2022). "The role of NF1 loss-of-function in the reactivation of the RAS/MAPK pathway upon BRAF inhibition was confirmed in multiple other melanoma cell lines and in an Nf1-knockout mouse model." (PMID 35234863, 2022). "The findings indicate a possible role for FER amplification in driving the MAPK pathway, similar to KIT, another receptor tyrosine kinase that can be amplified or mutated in acral and mucosal melanoma, frequently also in conjunction with NF1 mutations." (PMID 35706047, 2022). "This suggests that CCND1 amplification is mutually exclusive with BRAF, RAS, and NF1 mutations, which account for the three most common mutant genes observed in melanoma." (PMID 35844619, 2022). "The mutations of the NF1 gene were also observed in sporadic melanomas, but it is more common in melanomas after exposure of the skin to radiation, or wild-type melanomas, which include mutations in BRAF or Nras genes." (PMID 35053664, 2022). "Recently, it has been demonstrated that the NF1 gene mutation is merely a trigger for developing melanomas." (PMID 35053664, 2022). "Loss-of-function alterations of NF1 are present in almost 20% of melanomas and include missense or truncating mutations as well as chromosomal deletions." (PMID 35234863, 2022). "NF1 is a tumor suppressor gene, and its loss-of-function has been described in up to 10–15% of melanomas." (PMID 36064728, 2022). "Two studies found an association between NF1 and melanoma, and our study found a significantly increased risk for melanoma among patients with NF1 (OR, 3.9; 95% CI, 2.4-6.5; P < .0001)." (PMID 33734413, 2021). "Oncogenic BRAF, NRAS, NF1 mutations can activate the tyrosine kinase receptor EGFR resulting in enhanced ERK1/2 phosphorylation in melanoma." (PMID 34360915, 2021). "We found that the nevogenic melanomas were associated with mutations in BRAF, while the CSD melanomas were associated with mutations in NF1, ROS1, GNA11, and RAC1." (PMID 34680367, 2021). "Loss-of-function mutations of the NF1 tumor suppressor in human melanoma cells were first identified by us and others in the early 1990s." (PMID 34331013, 2021). "The NF1 mutation status was available for 66 melanoma samples: 51 patients presented at least one mutation in NF1, and 15 patients had wild type NF1." (PMID 34698264, 2021). "To validate the efficacy of our three-drug combination, we turned to studies using human NF1/PTEN-deficient melanoma cells." (PMID 34331013, 2021). "Although one of the main drivers in melanoma development is also NF1 mutation, the incidence of melanoma in NF1 patients is slightly elevated." (PMID 33530415, 2021). "Using The Cancer Genome Atlas (TCGA) dataset of skin cancers, we analyzed isomiR expression in primary melanoma and melanoma metastasis and tested their association with NF1, BRAF and NRAS mutations." (PMID 34698264, 2021). "These NF1 mutations are more common in melanomas occurring on chronically sun-exposed skin or in older patients, in melanomas with higher mutation burden, wild-type for BRAF and NRAS, and in the desmoplastic melanoma subtype." (PMID 34123788, 2021).
melanoma (continued). "In sum, these data bring new light on the transcriptome regulation of the NF1-mutated melanoma subgroup and will help improve the possibilities for specific treatment." (PMID 34362135, 2021). "NF1 mutation rates are 16% in MM and 15% in CM, suggesting NF1 plays a pivotal role in the biology of both types of melanoma." (PMID 34350118, 2021). "Here we show that loss-of-function mutations of nf1 and pten result in aggressive melanomas in zebrafish, representing the first animal model of NF1-mutant melanomas harboring PTEN loss." (PMID 34331013, 2021). "Though NF1 mutations often occur in melanomas without BRAF or NRAS mutations, approximately 4% of the BRAF and NRAS mutated melanomas also harbor NF1 mutations." (PMID 35008286, 2021). "Then, using WM-3246 cells, we tested the effects of sirolimus, venetoclax and S63845 on the viability of NF1/PTEN-deficient melanoma cells." (PMID 34331013, 2021). "The CSD melanomas, in contrast, showed mutations in a diverse group of genes that included NF1, ROS1, GNA11, and RAC1." (PMID 34680367, 2021). "We obtained the mutation status of BRAF, NRAS and NF1 for the melanoma samples from the TCGA database." (PMID 34698264, 2021). "Neurofibromin 1 (NF1) is a tumor suppressor, and loss of function mutations occur in this gene in 10–15% of melanomas and are especially prevalent in high-CSD melanomas (i.e., lentigo maligna)." (PMID 35008286, 2021). "The mutant of BRAF in melanoma patients has predicted a good survival and the NRAS or NF1-mutant subtype of melanoma was associated with poor outcomes." (PMID 34745259, 2021). "Melanomas driven by loss of the NF1 tumor suppressor have a high risk of treatment failure and effective therapies have not been developed." (PMID 34331013, 2021). "In BRAF V600E melanomas, loss of NF1, frequently co-occurring with BRAF and RAS alterations, allows a high level of activity of RAS-GTP and resistance to BRAF inhibitors." (PMID 32850962, 2020). "Other mutations frequently associated with NF1 loss in melanoma occur in PTPN11, SOS1, RAF1, SPRED1 and other genes." (PMID 32605090, 2020). "We further delineated the mutation patterns of 4 molecular subgroups (BRAF, RAS, NF1, and Triple-WT) of melanoma in our cohort." (PMID 32083130, 2020). "The frequency of ARID2 mutations among different melanoma genetic subtypes ranged from 2% in triple wild-type melanoma to 29% in NF1-mutant melanoma." (PMID 33024276, 2020). "Different studies have linked mutually exclusive mutations in the BRAF, NRAS, C-KIT, and NF-1 genes with the development of melanoma." (PMID 32775409, 2020). "Melanomas with NF1 mutations typically occur on chronically sun-exposed skin or in older individuals, show a high mutation burden, and are wild-type for BRAF and NRAS." (PMID 32393282, 2020). "NF1 mutations are detected in 15% of melanoma and the majority of them are from older patients with a higher mutational burden." (PMID 33256089, 2020). "The loss of a functional product of the NF1 gene contributes to one of the mechanisms of BRAFi resistance in melanoma." (PMID 32605090, 2020). "A previous study revealed numerous NF1 gene mutations in lung cancer, glioblastoma, melanoma and cutaneous NF1; however, to our knowledge, the literature exploring the NF1 mutations in OPPN patients is rather limited." (PMID 31533651, 2019). "Among these, activating mutations in BRAF and NRAS gene and inactivating mutations in NF1 gene accounts for over 80% of melanoma and results in the activation of MAP kinase pathway." (PMID 31217906, 2019). "Firstly, the BRAF status is determined; then, the RAS status, then NF1, and c-kit mutations are considered for acrolentiginous melanomas." (PMID 30357519, 2019). "NF1 mutated melanoma was previously associated with a higher mutational burden and elevated C>T transition." (PMID 31500314, 2019). "More recently discovered mutations in the neurofibromin 1 (NF1) gene account for 10% of all melanomas." (PMID 30987166, 2019).
melanoma (continued). "Two patients had a NF1 mutation, while all the other 13 patients were triple wild-type according to the molecular classification of melanoma." (PMID 31500314, 2019). "A clinical trial will investigate the effect of everolimus, sorafenib or trametinib in NF1-mutated melanoma (NCT02645149)." (PMID 31500314, 2019). "In summary, we used BRAFV600E- and NF1-loss-driven melanoma models to demonstrate that endogenous RAC1P29S promotes the progression of melanocytic hyperplasia to melanoma." (PMID 31257073, 2019). "Loss-of-function mutations in NF1 are frequently associated with a large variety of cancers, such as melanoma, leukemia, glioblastoma, and lung cancer." (PMID 30858928, 2019). "Activating mutations in the MAP2K1 (MEK1) oncogene and loss of the tumor suppressor gene neurofibromin 1 (NF1) are other frequent alterations in melanomas that activate the MAPK pathway, with frequencies of ~6% and ~13%, respectively." (PMID 31581557, 2019). "NF1 mutations were associated with initiation of melanoma and are prevalent in chronically sun-exposed skin." (PMID 29795011, 2018). "Alterations in BRAF, NRAS, and NF1 define the canonical genetic subtypes of melanoma, yet each of these oncogenic mutations is insufficient to drive tumorigenesis." (PMID 29875996, 2018). "Since NF1 is highly mutated in melanoma and various other cancer types, it is evident that this tumor suppressor plays an important role in cancer development and progression." (PMID 30131853, 2018). "The tumor suppressor gene NF1, coding for the neurofibromin protein, has recently emerged as one of the key drivers of melanoma, showing a high-frequency of mutations (12–18% of all melanoma cases)." (PMID 29534457, 2018). "NF1, which is mutated in 14% of melanoma patients, is a tumor suppressor gene that encodes a RAS GTPase activating protein (RAS GAP), which negatively regulates RAS by catalyzing the hydrolysis of RAS-GTP to RAS-GDP." (PMID 30131853, 2018). "Melanomas carrying NF1 mutations present with a higher mutational burden and a markedly evident UV mutation signature." (PMID 30218391, 2018). "Similar to cutaneous melanomas, conjunctival melanomas can be grouped genetically into four groups: BRAF-mutated, RAS-mutated, NF1-mutated and triple wild-type melanomas." (PMID 29559732, 2018). "In particular, inactivating NF1 mutations are present in 46% of melanomas expressing wild-type BRAF and RAS and are more commonly observed in chronically sun-exposed skin, desmoplastic melanomas." (PMID 29534457, 2018). "Third, we noticed that sporadic cancer with high mutation frequency for the NF1 gene (e.g. melanoma, glioblastoma, lung, skin, and ovarian cancer), rarely, if ever, develop in NF1 patients, although they have already lost one copy of NF1." (PMID 30479396, 2018). "NF1 protein, also known as neurofibromin 1, is considered a “driver” mutation in a subset of melanoma." (PMID 29795011, 2018). "The present study provides extensive characterization of genomic subtypes based on mutations in BRAF, RAS, and NF1 by using a large dataset comprising mutation data for 1461 genes in 864 clinically annotated melanomas." (PMID 28267273, 2017). "The TCGA network (The Cancer Genome Atlas Network) has now established a classification of cutaneous tumors according to their mutational status for genes BRAF, NRAS and NF1, all known as major actors of tumor initiation for melanoma." (PMID 29081790, 2017). "As with melanoma and neuroblastoma, inactivation of NF1 in breast cancer is associated with resistance to drug therapy." (PMID 28637487, 2017). "In line with previous observations, they confirmed that the NF1-mutated melanoma subtype had a higher mutational burden and displayed the strongest UV mutation signature." (PMID 29156643, 2017).
melanoma (continued). "In a recent study of a cohort of 75 tumours from patients with a mucosal melanoma, NF1 and RAS mutations were identified in 18.3 and 16.9% samples, respectively, whereas 8.4 and 7% of tumour samples harboured BRAF and KIT mutations." (PMID 28637487, 2017). "The direct involvement of NF1 in melanoma was first reported by Andersen and colleagues in 1993 who identified a homozygous NF1 deletion in one of eight malignant melanoma cell lines which resulted in the loss of detectable NF1 mRNA and neurofibromin protein." (PMID 28637487, 2017). "NF1 mutations were detected in 8% (8/100) of the melanomas; and nonsense mutations were the most prevalent alteration [62.5% (5/8)], including one recurrent mutation present in two samples (p.R1362*)." (PMID 28356599, 2017). "In mouse melanoma models, NF1 mutations cooperate with BRAF mutations in driving the development of melanoma by preventing oncogene-induced senescence, thus suggesting a role for NF1 in the early stages of tumor development." (PMID 29156643, 2017). "For melanomas with NF1 loss‐of‐function mutations or deletions, studies have shown that NF1 ablation can be linked to decreased sensitivity and resistance to BRAF inhibitors both in vitro and in vivo." (PMID 28267273, 2017). "The Cancer Genome Atlas proposed that NF1 mutations should be included for classification in BRAFwt/NRASwt melanoma, since reports were available showing that mutations in NF1 led to hyper-activation of the MAPK pathway and were responsive to MEK inhibition." (PMID 28350340, 2017). "Many subsequent studies have identified additional somatic NF1 mutations in melanoma in 12–30% of cases." (PMID 28637487, 2017). "In contrast, BRAF-mutant, NF1-deficient, and triple wild-type melanomas were relatively sensitive to these agents." (PMID 27608486, 2016). "RMEL3 expression was also significantly increased in melanomas with a BRAFV600E mutation compared to those with a wild type BRAF or triple wild type for BRAF/RAS/NF1, an association also observed in a panel of human melanoma cell lines." (PMID 27167340, 2016). "We did not observe similar changes in mRNA levels of E2F2 or its target genes after IFI6 knockdown in BRAF-mutant or NF1-deficient melanoma cell lines." (PMID 27608486, 2016). "To identify miR-514a regulated targets we conducted a miR-514a-mRNA ‘pull-down’ experiment, which revealed hundreds of genes, including: CTNNB1, CDK2, MC1R, and NF1, previously associated with melanoma." (PMID 25980496, 2015). "In mice injected with BRAF/NF1-mutated melanoma cells, there was resistance to vemurafenib, a BRAF inhibitor." (PMID 25026295, 2014). "NF1 mutations were observed in melanoma tumors obtained from patients exhibiting resistance to vemurafenib, as already mentioned." (PMID 24743024, 2014). "The last subtype of melanoma was typically associated with more advanced age, and 30% of melanomas from this class (10/33 samples) carried deleterious NF1 mutations." (PMID 25026295, 2014). "In a mouse model study, NF1 mutations cooperate with BRAF mutations in the pathogenesis of melanomas by preventing oncogene-induced senescence." (PMID 25026295, 2014). "In our study, analysis of NF1 allele status in a formalin-fixed melanoma specimen necessitated the combination of liquid coverslip laser microdissection, microsatellite analysis and digital PCR." (PMID 16961930, 2006). "Deletion of the NF1 gene in NF1-associated melanoma suggests that the NF1 genetic background promoted melanoma genesis." (PMID 16961930, 2006). "It has been reported previously that melanoma in NF1 tends to arise at younger age and mutation detection in an early tumor stage is a stronger indication of a causative role of the detected mutation than mutation detection in a late stage malignant tumor." (PMID 16961930, 2006).